SMAD4 (SMAD family member 4)
Diseases named in the same sentence as SMAD4 in open-access papers (continued):
Sharing a sentence is not in itself a finding about the gene and the disease.
lymph node metastasis (continued). "The advantage of SMAD4 expression as a prognostic indicator is that it is potentially assessable preoperatively in comparison to tumor size, resection margins, perineural invasion, and lymph node metastasis, which can only be accurately evaluated after surgery." (PMID 17587453, 2007). "Loss of nuclear Smad4 expression in tumor was associated with presence of lymph node metastasis, but no influence on prognosis could be demonstrated." (PMID 17692120, 2007). "SMAD4 expression is lower in NSCLC and correlated with lymph node metastasis, tumor differentiation, tumor node metastasis stage and good OS for NSCLC patients." (PMID 37478236, 2023). "The expression of Smad4 in NSCLC tissues was lower than that in normal lung tissues (P = 0.009) and its expression was related to the degree of tissue differentiation, lymph node metastasis and clinical stage (P < 0.05)." (PMID 33794845, 2021). "And the expression of Smad4 in NSCLC tissues with N2–N3 stage (20%; 3/15) of lymph node metastasis was lower than in NSCLC tissues with N0–N1 (59.5%; 22/37) stage (P = 0.010)." (PMID 33794845, 2021). "In this study, we found that SMAD4 is correlated with tumor differentiation, lymph node metastasis and the TNM stage of NSCLC patients but is not correlated with age or sex." (PMID 37478236, 2023). "Our study explored the changes of Smad4 in NSCLC and showed that its change could be used as a potential indicator for evaluating the degree of NSCLC differentiation and lymph node metastasis." (PMID 33794845, 2021). "NSCLC reportedly features low Smad4 expression, which is closely correlated with lymph node metastasis but not with histological type or differentiation." (PMID 25890228, 2015). "More nodal positive tumours (93% or 122 of 131) than cases without lymph node metastasis (80% or 139 of 174) showed nuclear Smad4 expression (p = 0.004)." (PMID 17692120, 2007). "In our meta-analysis, we found that SMAD4 expression is correlated with tumor differentiation, lymph node metastasis and TNM stage but not with the age or sex of NSCLC patients and SMAD4 expression is lower in NSCLC and is correlated with good OS of NSCLC patients." (PMID 37478236, 2023).
invasive carcinoma (20 papers, 2005 to 2025). A carcinoma that is not confined to the epithelium, and has spread to the surrounding stroma. "Regarding MCNs, the prevalence of SMAD4 alterations is reported as very low in the noninvasive component, but higher in the associated invasive carcinoma." (PMID 40371932, 2025). "For example, the analysis of the Smad4 gene in colorectal carcinomas showed mutations in 7 percent of the samples of primary invasive carcinoma without distant metastasis, but mutations in 35 percent of the samples of primary invasive carcinoma with distant metastasis." (PMID 20822525, 2010). "In contrast, SMAD4 had alterations confined to the invasive carcinoma in three cases and was shared between noninvasive and invasive samples in four cases." (PMID 32796935, 2020). "Mutations in SMAD4 and TGFBR2 are frequently restricted to invasive carcinoma, while RNF43 alterations are largely in non-invasive lesions." (PMID 32796935, 2020). "This on-off pattern for PTEN, SMAD4 and most stem cell markers is abrogated in the invasive carcinoma away from this adenomatous junction." (PMID 26098881, 2015). "For example, SMAD4 mutations are not typical of pancreatic intraductal papillary mucinous neoplasms but occur in up to 16% of invasive carcinomas that are associated with IPMN." (PMID 30730996, 2019). "Loss of SMAD4 expression limited to invasive carcinomas has been reported in MCN- and IPMN-associated invasive cancers, and targeted sequencing of a small number of IPMNs and matched cancers identified a single case with a SMAD4 mutation occurring only in the cancer." (PMID 32796935, 2020). "In IPMN without invasive carcinoma, LOH at the SMAD4 locus is frequent." (PMID 24278753, 2012).
non-small cell lung carcinoma (20 papers, 2015 to 2025). A group of at least three distinct histological types of lung cancer, including non-small cell squamous cell carcinoma, adenocarcinoma, and large cell carcinoma. "Multiple studies have shown that miRNAs like miR-205 promote tumor progression in non-small cell lung cancer (NSCLC) by downregulating SMAD4 to inhibit p21 expression, while miR-146a-5p and miR-15a suppress cell cycle progression by targeting Cyclin D1/D2." (PMID 41002349, 2025). "A recent study provided evidence indicating that tranilast inhibited TGF-β1-induced epithelial–mesenchymal transition (EMT), tumor invasiveness, and metastasis by suppressing Smad4 expression in human non-small cell lung cancer." (PMID 37445642, 2023). "Another study demonstrated that miR-1285 influenced the proliferation and metastasis of non-small-cell lung carcinoma cells through the downregulation of Smad4." (PMID 34383767, 2021). "For example, miR-205 targets the tumour suppressor factor SMAD4 to accelerate cell cycle progression in non-small cell lung cancer cells." (PMID 32014006, 2020). "For example, miRNA-205 targets the tumour suppressor SMAD4 to accelerate cell cycle progression in non-small cell lung cancer cells." (PMID 32014006, 2020). "It has been reported that miR-205 can promote cell proliferation by inhibiting SMAD4 gene expression in non-small cell lung cancer cells and promote tumor growth in nude mice." (PMID 32596241, 2020). "Moreover, miR-1285 was shown to affect the proliferation and metastasis of non-small-cell lung carcinoma cells by downregulating Smad4, a central mediator of TGF-β intracellular signaling." (PMID 34383767, 2021). "Moreover, the increased expression of miR-1285-5p in non-small cell lung cancer tissues suggests its role as a potential promoter of tumor development, regulating critical behaviors, such as proliferation, invasion, and migration through interactions with genes, such as Smad4 and CDH1." (PMID 37895471, 2023). "The relationship between SMAD family member 4 (SMAD4) and the clinicopathological and prognostic significance of non-small cell lung cancer (NSCLC) patients is unclear." (PMID 37478236, 2023). "CRCA (cis-Apc+/Δ716/Smad4+/- mice) and LNCA (K-rasLSL-G12D/+/p53lox/lox mice) are genetically engineered mouse models for colorectal and non-small cell lung cancer, respectively." (PMID 37803016, 2023). "Transformation to SCLC is irrespective of EFGR status and can be accelerated by SMAD4 in non-small cell lung cancer." (PMID 38233864, 2024). "The aim of the present study was to investigate the expression levels of transforming growth factor-β (TGF-β) receptor type II (TβRII) and DPC4/Smad4 in the TGF-β signaling pathway and the importance of these expression levels in non-small cell lung cancer (NSCLC)." (PMID 25452807, 2015).
cholangiocarcinoma (19 papers, 2007 to 2025). A carcinoma that arises from the intrahepatic biliary tree (intrahepatic cholangiocarcinoma) or from the junction, or adjacent to the junction, of the right and left hepatic ducts (hilar cholangiocarcinoma). "In cancer signaling, SMAD4 was a tumor suppressor whose deficiency commonly occurred in pancreatic, colorectal, cholangiocarcinoma and many other less common cancers and was associated with pathological stages." (PMID 37895906, 2023). "A further probably pathogenic heterozygous SMAD4 variant (NM_005359.5) c.380G>T (p.Cys127Phe) was identified in a patient with multiple stomach polyps and primary cholangiocarcinoma." (PMID 24307375, 2014). "Commonly associated genomic mutations associated with cholangiocarcinoma include KRAS, BRAF, p52, and SMAD4 genes." (PMID 38903278, 2024). "For instance, PAK1 has been reported to increase pemigatinib resistance in cholangiocarcinoma through β-catenin/Smad4-mediated pathways." (PMID 37537668, 2023). "In studies of SMAD4 in biliary tract cancer, organ-specific disruption of SMAD4 was shown to induce tumorigenesis of cholangiocarcinoma." (PMID 36088360, 2022). "SMAD4 is also a direct target of miR-34a-5p in cholangiocarcinoma (CC)." (PMID 28340489, 2017). "We identify miR-34a could mediate TGF-β/Smad4 signaling pathway induced EMT in the progression of cholangiocarcinoma." (PMID 26077733, 2015). "Moreover, both miR-34a and TGF-β/Smad4 pathway have been shown to involve in mediating metastasis and invasion in various types of cancers including cholangiocarcinoma." (PMID 26077733, 2015). "In cholangiocarcinoma, next-generation sequencing of 31 cholangiocarcinoma cases identified SMAD4 as a favourable prognostic biomarker in intrahepatic CCA and perihilar CCA by univariate and multivariate analysis." (PMID 37685308, 2023). "SMAD4 inhibited the proliferation, migration, and invasion of CCA, and enhanced the sensitivity of cholangiocarcinoma to pemotinib, the only FDA-approved targeted drug for CCA by inhibiting β-catenin-S675 phosphorylation and intranuclear translocation." (PMID 37685308, 2023). "SMAD4 is a tumour suppressor and an important regulator of tumour immune scape which is downregulated in cholangiocarcinoma (CCA)." (PMID 37488750, 2023).
liver cancer (18 papers, 2011 to 2025). An epithelial or non-epithelial malignant neoplasm that arises from the liver. "Furthermore, previous studies have demonstrated that Pten loss potentiates ICC formation on the background of steatosis (fatty liver) and interacts with Smad4-loss to initiate liver cancer." (PMID 35074757, 2022). "Thus, liver cancer cells appear to hijack Smad2/3 and Smad4 for CSCs, and this process is closely associated with oncogene cyclin D1 regulation." (PMID 28415588, 2017). "The mutation of other genes, including β-catenin, SMAD2, SMAD4, p16 INK4a, and Cyclin D1, may also be implicated in liver cancer." (PMID 22091434, 2011). "In conclusion, our study observed an epigenetic control of TGFβ functional duality in liver cancer, SMAD4 demethylation being identified as a tumor-suppressive event possibly preventing tumor metastasis and recurrence in early HCC." (PMID 34571856, 2021). "In this study, we found that LINC01234 knockdown downregulated the expression of p-Smad2, p-Smad3 in liver cancer cells and increased the level of Smad4 in Cytoplasm of Huh-7 cells." (PMID 33178601, 2020). "Additionally, USP10 can also stabilize Smad4 by ubiquitinating it, which contributes to liver cancer metastasis." (PMID 37143582, 2023). "Similarly, we found that the expression of Smad2/3 and Smad4 directly promotes liver cancer spherogenesis and consequently confers these cells with high stemness and CSC properties." (PMID 28415588, 2017). "Smad4, the central mediator of TGF-β signaling, is also involved in key development processes of liver inflammation 14, fibrosis 15, fatty liver 16, and liver cancer." (PMID 39346534, 2024). "To further explore the role of Smad4 in HCC, we established a mouse fibrosis related liver cancer model using DEN/CCl4 treatment." (PMID 39346534, 2024). "USP10 stabilizes Smad4 by ubiquitinating it, activates TGF‐β signaling, and promotes liver cancer metastasis." (PMID 37143582, 2023). "In the RT-PCR analysis, we found that in both of the two liver cancer cell lines, the expression of CTNNB1 and SMAD4 was greatly inhibited by PS341 while the other four stemness-related genes remained almost the same (top)." (PMID 26915315, 2016). "HBx also regulates the interaction between critical proteins, glucose‐regulated protein 78 (GRP78) and tripartite motif containing 25 (TRIM25) through ubiquitination, reducing TRIM25 ubiquitination levels, which increases SMAD family member 4 (SMAD4) activity and drives liver cancer progression." (PMID 40060195, 2025).
esophageal cancer (17 papers, 2006 to 2025). A primary or metastatic malignant neoplasm involving the esophagus. "CDCA7 promotes TGF-β-induced epithelial-mesenchymal transition to promote tumor progression by transcriptionally regulating Smad4/Smad7 in esophageal cancer cells." (PMID 39905019, 2025). "Consistent with our study, a recent study in esophageal cancer also demonstrated that TGF-β signaling pathway functioned in a Smad4-independent way." (PMID 33757572, 2021). "In esophageal cancer, the loss of SMAD4 correlates with the invasion depth and the pathologic stage as well as with regional metastases and with decreased survival.In animal models for HNSCC, SMAD4 haploid insufficiency promoted tumor development." (PMID 31867281, 2019). "Of the SMAD4 mutations (p.R361H, p.G386S and p.D404E), p.R361H and p.G386S have been found in many cancers, including colon, stomach and esophageal cancers, while p.D404E is a novel mutation that has not been reported." (PMID 28179590, 2017).
lung adenocarcinoma (17 papers, 2015 to 2026). A carcinoma that arises from the lung and is characterized by the presence of malignant glandular epithelial cells. "Increasingly, novel genes such as SMARCA1, SMARCA4 and SMAD4 alterations in lung adenocarcinoma are independently associated with LNM in lung adenocarcinoma." (PMID 39720561, 2024). "Mutations of TGFβR-II and SMAD4 are rare in NSCLC, whereas epidermal growth factor receptor (EGFR) and KRAS mutations are frequently found in lung adenocarcinomas." (PMID 30127261, 2018). "After revealing the prognostic role of FSTL1, BMP4, and Smad4 in lung adenocarcinoma, we further analyzed their expression correlations." (PMID 28852126, 2017). "In lung adenocarcinoma of our patient cohort and public dataset, FSTL1 expression had positive correlation with BMP4-p-Smad1/5/8-Smad4 expression level and loss of FSTL1, BMP4, and Smad4 expression had a similar trend to predict poor prognosis." (PMID 28852126, 2017). "In lung adenocarcinoma, SMAD4 has been detected in cerebrospinal fluid circulating tumor DNA27." (PMID 37076495, 2023). "In conclusion, we provide insight into the biological function of AK2 in human lung adenocarcinoma and demonstrate that AK2 overexpression activates the TGF-β/Smad3/Smad2/Smad4 signaling pathway, leading to enhanced invasion via EMT." (PMID 34630090, 2021). "Lung adenocarcinoma patients with low FSTL1, BMP4, or Smad4 expression had poor prognosis." (PMID 28852126, 2017). "When stratified by different histological types, low FSTL1, BMP4, and Smad4 expression retained their trends in predicting poor prognosis in lung adenocarcinoma (LUAD) but not in lung squamous cell carcinoma (SCC)." (PMID 28852126, 2017). "In conclusion, current study revealed that low FSTL1, BMP4, and Smad4 expression significantly predict poor prognosis in lung adenocarcinoma but not in squamous cell carcinoma." (PMID 28852126, 2017). "We only observe a significant inverse correlation between miR-301a and Smad4 levels in lung adenocarcinoma, but not in lung squamous cell carcinoma, which indicate that other potential miR-301a targets probably participant the process of cell transformation and tumorigenesis." (PMID 30185897, 2018). "Interestingly, miR-301a also show inverse correlation with SMAD4 in lung adenocarcinoma, while it did not display significant anti-correlation to Smad4 in lung squamous cell carcinoma, suggesting the complex network of miRNA regulation during tumorigenesis." (PMID 30185897, 2018).